THBS2 (thrombospondin 2)
Diseases named in the same sentence as THBS2 in open-access papers (continued):
Sharing a sentence is not in itself a finding about the gene and the disease.
thoracic aortic aneurysm (1 paper, 2020). An aneurysm formed in the wall of the proximal portion of the descending aorta proceeding from the arch of the aorta. "THBS2 has been previously related to cardiovascular mortality in AAA patients, and even a previous study related a polymorphism in the THBS2 gene with thoracic aortic aneurysm." (PMID 32605321, 2020).
thyroid tumor (1 paper, 2023). A benign or malignant neoplasm affecting the thyroid gland. "Among the identified hub genes, AEBP1, CD34, COL12A1, ITGA2B, THBS2, and TPO exhibit lower expression levels in thyroid tumors." (PMID 37795451, 2023).
ulcers (1 paper, 2022). "THBS-2 expression was down-regulated in vitro in SSc dermal fibroblasts; on the other hand, it was found to be increased in the skin and serum of subjects with scars and/or ulcers." (PMID 36014018, 2022).
Ureteral obstruction (1 paper, 2019). Obstruction of the flow of urine through the ureter. "Otherwise, many of these genes, such as Agt, Ccl12, Col3a1, Dcn, Itgb6, and Thbs2, were temporarily changed in these MSLCs expanded from the left kidney at only 7 days after ureteral obstruction, but the changes of Ccl3 and Cxcr4 were constantly observed during the 14 days of follow-up." (PMID 30949209, 2019).
tumor (194 papers, 2002 to 2026). "A recent study demonstrated that THBS2 secreted by cancer-associated fibroblasts (CAFs) promotes CRC progression by binding to CD47 on tumour cells and activating the MAPK/ERK5 signalling cascade." (PMID 40860666, 2025). "THBS2, a matricellular glycoprotein, has been previously implicated in promoting tumor angiogenesis and metastasis." (PMID 41291892, 2025). "Several studies have mentioned that THBS2 expression is also associated with remodeling of the tumor immune microenvironment." (PMID 39020380, 2024). "Our data extend the role of THBS1 and THBS2, which are not only able to hinder the vascular network and promote tumor-associated lymphangiogenesis but also exacerbate the malignant behavior of the iCCA cells." (PMID 38339060, 2024). "The protein encoded by THBS2 has been shown to function as a potent inhibitor of tumor growth and angiogenesis." (PMID 37777726, 2023). "According to the literature, THBS2 is frequently mutated in a variety of cancers, and its high expression promotes tumor growth and distant metastasis." (PMID 37024829, 2023). "THBS2+ CAFs interact with macrophages and CD8+ T and B lymphocytes in the early LUAD tumor microenvironment, and high THBS2 in LUAD is associated with reduced immune cell infiltration and elevated immune exhaustion markers." (PMID 37187527, 2023). "THBS2 expression was upregulated in a majority of tumours, including COAD, and was positively associated with ESTIMATEScore, ImmuneScore and StromalScore." (PMID 37884956, 2023). "We found that overexpression of THBS2 can reverse the tumor-suppressing effects caused by AGAP2-AS1 knockdown." (PMID 38110984, 2023). "3G), in agreement with our findings showing the association of high THBS2 expression with tumor relapse." (PMID 35547750, 2022). "This study aimed to determine THBS2 expression in a pan-cancer analysis and its association with pan-cancer prognosis and to further identify its possible roles in tumor immunity and the extracellular matrix (ECM)." (PMID 35701829, 2022). "Several studies have reported that the mRNA levels of THBS2 were elevated in tumor tissues and that higher THBS2 expression was associated with a worse prognosis of patients." (PMID 34804159, 2021). "mRNA vaccines encoding these tumor antigens (THBS2, FSTL3, TNNT1, BGN, CTHRC1, and NOX4) induce a cell-mediated immune response and humoral immune response that are beneficial for efficient clearance of cancer cells." (PMID 35127707, 2021). "INHBA and THBS2 from cancer-associated fibroblasts are packaged into extracellular vesicles and secreted into the tumor microenvironment to promote gastric cancer." (PMID 34064083, 2021). "The analysis of the clinical characteristics showed that the high protein expression of THBS2 was closely associated with tumor size and its pathological stage." (PMID 33244454, 2020). "In many tumors, the expression of THBS2 in tissues is associated with tumor progression and overall survival." (PMID 31296790, 2019). "THBS2 has been shown to function as a potent inhibitor of tumor growth and angiogenesis, and was associated with many kinds of diseases." (PMID 28796930, 2017). "Capability of THBS2 mutations to have a dominant effect is well in line with the fact that somatic heterozygous THBS2 pathogenic variants can serve as cancerous driver, enabling tumor expansion through the disorganized extracellular matrix caused by the same processes shown in this study." (PMID 38433265, 2024). "Similarly, whereas THBS2 overexpression was associated with tumours located in the rectum, downregulated expression levels of ADH1B mRNA were more frequent in tumours situated in the colon (p = 0.02) at advanced stages (T3–T4; p = 0.04)." (PMID 36077612, 2022). "Moreover, PMEPA1 knockout is known to impair tumor growth, and THBS2 overexpression is known to be associated with vascular invasion, advanced primary tumor status and nodal metastasis." (PMID 34674656, 2021).
tumor (continued). "Thus, it is possible that THBS2 is an important factor mediating tumor-associated macrophages/DCs and tumor metastasis." (PMID 34804159, 2021). "The majority of proteins (ACTR2, CSTB, LTA4H, PGK1, NDRG1, FSCN1, ITGAV, THBS2) significantly associated with clinical parameters showed lower expression in the ITF of the tumor stroma or neoplastic islands, with the exception of COL6A1, COL1A2, S100A8, S110A9, and MB." (PMID 30185791, 2018). "THBS2 may be a multi-function molecule, inhibiting both tumor-associated angiogenesis and local immune responses." (PMID 27513329, 2016). "Furthermore, THBS2 expression was positively associated with angiogenesis and epithelial–mesenchymal transition and negatively associated with DNA repair, cell cycle and DNA replication in most tumours." (PMID 37884956, 2023). "Furthermore, highly expression of BGN and THBS2 in tumours was linked to a worse survival rate." (PMID 36377223, 2022). "Moreover, THBS2 is also correlated with tumor-associated immune cell infiltrations." (PMID 34804159, 2021). "Interestingly, THBS2 is associated with tumor growth in adult mouse tissues." (PMID 21989116, 2011). "The analysis identified miR‐93‐5p binding sites within the 3′‐UTRs of several key tumor‐associated genes, including PTEN, CDKN1A (p21), TP53INP1, and THBS2." (PMID 41159542, 2026). "For instance, in PDAC, CAF-derived thrombospondin 2 (THBS2) drives tumor progression via integrin αvβ3/CD36-mediated signaling." (PMID 40520021, 2025). "Regarding our findings, several hub genes, including ADAM12, MET, THBS2, ZEB1, and ZEB2, have been previously implicated in PDAC progression, tumor invasiveness, and epithelial–mesenchymal transition (EMT)." (PMID 40728965, 2025). "Specifically, high protein expression of THBS2 was observed in tumor tissues, whereas normal tissues displayed low levels." (PMID 41291892, 2025). "It was shown that knockout mice of THBS2 have an increased bleeding time phenotype (MP:0005606) and THBS2 is a potent inhibitor of tumor growth and angiogenesis." (PMID 40179105, 2025). "COL12A1 and THBS2 showed enriched expression in tumor tissue section and hyaluronan and proteoglycan link protein 1 (HAPLN1) showed enriched expression in NAT tissue section." (PMID 40032993, 2025). "Although THBS1 and THBS2 directly affect iCCA tumor cells by enhancing their malignant traits, the direct role of PEDF in iCCA cells remains unexplored." (PMID 40001923, 2025). "THBS2 plays a critical role in the remodeling of the tumor microenvironment, the promotion of tumor angiogenesis, and cancer cell migration and invasion." (PMID 40141965, 2025). "Our results demonstrated that ALPPL2+ and THBS2+ exosome concentrations correlated competently with radiographic tumor burden (tumor size based on RECIST 1.1) in patients with PDAC regardless of their CA19-9 secretion status." (PMID 40897818, 2025). "THBS2 can influence tumor cell proliferation, migration, and invasion, contributing to CRC progression." (PMID 40242441, 2025). "Here, we discovered that THBS2 can be secreted by tumor cells into culture media through exosomes and that exosomal THBS2 can be transported into macrophages and induce M2 polarization by activating the Wnt signaling pathway." (PMID 39020380, 2024). "We evaluated the correlation of THBS2 level with the proportion of tumor-infiltrating immune cells as well as immune response in TCGA CRC datasets using the CIBERSORT algorithm and Spearman’s analysis." (PMID 39020380, 2024). "Thrombospondin-2 (THBS2) is a glycoprotein of the extracellular matrix that effectively prevents tumor development and angiogenesis." (PMID 38331927, 2024). "In particular, these highly expressed genes were notably associated with tumor development and metastatic progression, including A2M, AREG, chemokines (iCAFs-S1), BGN, MFAP5, THBS2, and TIMP1 (iCAFs-S2)." (PMID 39323622, 2024).
tumor (continued). "Six weeks after the injection, a significant reduction in liver metastasis was observed following RP11-417E7.1 knockdown, whereas THBS2 overexpression counteracted the inhibitory effect of shRP11-417E7.1 on tumor metastasis." (PMID 39020380, 2024). "Only THBS2 and CD163 exhibited somatic mutations in 6.14% (25/407) and 5.90% (24/407) of patients with tumor, respectively, with the remaining genes showing mutation frequencies below 2%." (PMID 38577604, 2024). "In the iCCA TME, we previously demonstrated that THBS1 and THBS2 are mainly expressed and released by CAFs and only to a lesser degree by tumor cells." (PMID 38339060, 2024). "Up-regulation in BGN, PEDF, THBS-2, and βIGH3 associated with PDAC progression, as players in tumor microenvironment, cell proliferation, or angiogenic processes." (PMID 39062863, 2024). "Generally, THBS1 was primarily found in fibroblasts, endothelial cells, and mononuclear macrophage cells, THBS3 was mostly expressed in fibroblasts, tumor cells and T cells, whereas THBS2, THBS4 and COMP were mainly found in fibroblasts." (PMID 38827236, 2024). "A box plot was generated to demonstrate the differential expression of THBS2 between tumour and normal tissues in 16 solid tumour cohorts." (PMID 37884956, 2023). "A CT26-THBS2 tumour-bearing mouse model was constructed to validate the impact of high THBS2 expression in tumour cells on the tumour microenvironment in vivo." (PMID 37884956, 2023). "THBS2, a member of the extracellular matrix glycoprotein family, can effectively inhibit tumour growth and angiogenesis." (PMID 37884956, 2023). "THBS2, is an adhesive glycoprotein that mediates cell-to-cell and cell to-matrix interactions, suggesting a role in escape and dissemination of the tumor cells." (PMID 38156105, 2023). "RT-qPCR and Western blot analysis results showed that, when compared with the adjacent normal tissues, THBS2 was highly expressed in the tumor tissues of NSCLC patients." (PMID 36609437, 2023). "Analyses of the GEO and TCGA databases revealed the upregulation of THBS2 in GC tumor tissues relative to normal paracancerous tissues (TCGA: P<0.01; GSE66229: P=0.003; GSE54129: P<0.0001; GSE27342: P<0.0001)." (PMID 36969001, 2023). "Altogether, these results suggest that THBS2 enhances anaerobic glycolysis in tumour cells by modulating the nuclear translocation of HIF1." (PMID 37884956, 2023). "The most important finding in this study is that the expression levels of the fibroblast biomarkers FOXQ1, MMP11 and THBS2 are significantly elevated in both primary tumor tissue and H&E(+)LNs of CC patients." (PMID 38156105, 2023). "THBS2 (thrombospondin 2), BASP1 (brain acid soluble protein 1), and NPR3 (natriuretic peptide receptor 3) are tumor-suppressor genes, for which downregulation is associated with poor prognosis." (PMID 36980828, 2023). "Taken together, these results suggested that depletion of the THBS2 gene can reduce the tumor-promoting ability of BMSC-MVs in nude mouse xenografts." (PMID 37798762, 2023). "We also found significantly upregulated myCAF markers in gal 4–KD tumor CAFs, including Col12a1, Col8a1, Thbs2, and Igfbp3." (PMID 36478037, 2023). "Immunomorphometry analyses revealed that FOXQ1-, MMP11- and THBS2-positive cells were present at significantly higher numbers in the CC tumor region than in normal colon epithelium (P < 0.0001)." (PMID 38156105, 2023). "In conclusion, this study reveals the pivotal role of THBS2 in the tumour microenvironment, highlighting its involvement in regulating lactate metabolism and M2 polarisation." (PMID 37884956, 2023). "The expression of THBS2 varies among cancers, and its precise relevance as a driver of tumor progression is still the subject of controversy." (PMID 36969001, 2023). "Potential correlation between levels of the fibroblast biomarkers FOXQ1, MMP11 and THBS2 in primary tumor tissue was investigated." (PMID 38156105, 2023).
tumor (continued). "Upregulated THBS2 expression in CRC cells inhibits anti-tumour immunity through the HIF1A/lactic acid/GPR132 pathway." (PMID 37884956, 2023). "Depletion of the THBS2 gene reduces the tumor-promoting ability of BMSC-MVs in an H. pylori infection microenvironment both in vitro and in vivo." (PMID 37798762, 2023). "Functionally, CAFs-derived THBS2 promoted the aggressive phenotype by presumably modulating both cancer cells and tumor immunity, identifying THBS2+ CAFs as a candidate therapeutic target in early-stage LUAD." (PMID 35547750, 2022). "Overall, in the TME, THBS2 expression was positively correlated with tumor-promoting immune infiltrating cells and negatively correlated with tumor-suppressing immune infiltrating cells." (PMID 35701829, 2022). "In recent studies, THBS2 has been considered as oncogene or biomarker in tumor development and progression." (PMID 35982904, 2022). "We previously reported that thrombospondin-2 (TSP2) expression was increased in tumor specimens from rat models, promoting excitatory synapse formation." (PMID 36476392, 2022). "Overall, we uncovered a biomarker THBS2, produced by a subset of tumor-specific THBS2+ CAF subpopulation, to stratify a subgroup of early-stage LUAD patients." (PMID 35547750, 2022). "A study on mouse models shows that THBS2 probably is a host anti-tumor defense mechanism with an anti-angiogenic mechanism." (PMID 36415513, 2022). "In general, our results showed the positive regulation of genes associated with processes related to tumour progression and metastatic process, including genes involved in extracellular matrix (ECM) interaction and cell adhesion, such as SPP1 and THBS2." (PMID 36077612, 2022). "The present study found that THBS2 expression was significantly related to the abundance of various immune cells in various tumor types." (PMID 35701829, 2022). "THBS2 (thrombospondin-2) is a secreted matricellular glycoprotein that is closely related to tumor occurrence and metastasis." (PMID 36195908, 2022). "This study showed that the abundance of macrophages and NK cells in the tumor microenvironment of GC with high THBS2 expression was higher than that of GC with low THBS2 expression, while the abundance of Th17 cells was lower." (PMID 35186032, 2022). "We found that increased expression of two markers, thrombospondin 2 (THBS2) and transgelin (TAGLN), was associated with poorer OS in MOC after adjustment for age and tumor stage." (PMID 36222710, 2022). "A study conducted by Grunberg suggested that HSF1 upregulated inhibin subunit beta A (INHBA) and thrombospondin 2 (THBS2), which are involved in tumor progression." (PMID 34064083, 2021). "THBS-2 is a glycoprotein present in the extracellular matrix; by inhibiting tumor angiogenesis, it controls tumor growth and is considered to be one of the body’s defensive anti-cancer mechanisms." (PMID 34830745, 2021). "Among them, thrombospondin‐2 (THBS2) was significantly increased in PDAC tumor tissue and plasma samples (p < 0.001, AUC = 0.844), and the combined detection of THBS2 and CA19-9 had high accuracy in the diagnosis of PDAC (AUC = 0.952)." (PMID 34707986, 2021). "In multiple cancers, decreasing the expression of THBS2 can trigger production of oncogenes or depress production of tumor suppresser genes." (PMID 34659407, 2021). "THBS2 also affects the proteolysis of tumor cytoplasm, thereby contributing to certain proteins in the PI3K/AKT signaling pathway." (PMID 33345281, 2021). "In the future study, it will be more convincing and meaningful to demonstrate the role of THBS2 in tumor metastasis through knockout or knock-in animal models." (PMID 34804159, 2021). "THBS2 was identified as a potent inhibitor of angiogenesis and tumor growth, while promoting cell adhesion and migration." (PMID 33345281, 2021).